PKIB (cAMP-dependent protein kinase inhibitor beta)
Diseases named in the same sentence as PKIB in open-access papers (continued):
Sharing a sentence is not in itself a finding about the gene and the disease.
cancer (9 papers, 2014 to 2025). A tumor composed of atypical neoplastic, often pleomorphic cells that invade other tissues. "Hormonal signaling is correlated with increased PKIB expression through genetic regulation, and increasing PKIB expression is associated with decreased cancer patient prognosis." (PMID 38731883, 2024). "This study highlights the potential of PKIB as both a diagnostic and prognostic marker in early cancers." (PMID 38731883, 2024). "Inflammatory bowel disease has PKIB overexpression, and as cancer is associated with inflammation, there may be some crossover." (PMID 38731883, 2024). "In addition, genetic regulation in cancer has been linked to PKIB for hypoxia-inducible factors (HIF1α and HIF2α)." (PMID 38731883, 2024). "Cyclic AMP-dependent protein kinase A (PKA) is recognized for its pivotal involvement in various cancer types, with Protein Kinase Inhibitor Beta (PKIB) serving as an endogenous inhibitor that curtails PKA activity." (PMID 40593489, 2025). "Despite the documented escalation of PKIB expression in several malignancies, a comprehensive understanding of its precise mechanistic implications in human cancers remains elusive." (PMID 40593489, 2025). "A few studies have reported the abnormal overexpression of PKIB in a range of cancers, suggesting its potential role in tumorigenesis." (PMID 40593489, 2025). "Although PKIB is abnormally overexpressed in various cancers and promotes tumorigenesis, the detailed molecular mechanisms by which PKIB regulates tumor progression are unclear." (PMID 40593489, 2025). "The study of the mechanisms and activities of PKI against PKA in cancer is a growing field, and this review aims to summarize the research specifically about PKIB." (PMID 38731883, 2024). "With a PKIB-specific inhibitor, it would be easier to understand the interactions and mechanisms of PKIB-altered diseases and cancers." (PMID 38731883, 2024). "For example, the potential of PKIB as a cancerous biomarker provides another possible target for multi-cancer treatment." (PMID 38731883, 2024). "The goal of this review is to highlight the potential of PKIB in cancer research with a focus on elucidating the role PKIB plays in cancer development and possible treatment options." (PMID 38731883, 2024). "Following the stem cell model of cancer development, it would be interesting to see how the levels of PKIB change, if at all." (PMID 38731883, 2024). "The impact of PKIB expression varies between cancer types as well as the tissue of origination of the tumor." (PMID 38731883, 2024). "It would be particularly interesting to see how primary tumor sites and secondary metastatic locations differ in PKIB expression, especially considering the transition from mesenchymal back to epithelial cancer cells in a distant location." (PMID 38731883, 2024). "The expression levels of E-cadherin and vimentin, two documented metastatic factors, are regulated by PKIB, thus demonstrating an impact of PKIB expression on cancer metastasis." (PMID 38731883, 2024). "While there is scattered knowledge about the multi-variate roles of PKIB in cancer and cancer development, there are few firm conclusions that can be drawn to paint PKIB as either oncogenic or protective." (PMID 38731883, 2024). "Cancer genomic and proteomic analyses of PKIB, using The Cancer Genome Atlas program, have shown that the most common PKIB alterations are deep deletions and amplifications." (PMID 38731883, 2024). "Although PKIB has been reported to be upregulated in a variety of cancers, the regulatory mechanisms leading to its abnormal overexpression are unknown." (PMID 40593489, 2025). "These evidences imply a significant potential oncogenic function of PKIB in multiple cancer types." (PMID 40593489, 2025). "As expected from the common nature of PKA, PKIB is involved in multiple aspects of cancer." (PMID 38731883, 2024). "The limited research into PKIB indicates the oncogenic potential of PKIB in various cancers." (PMID 38731883, 2024).
cancer (continued). "However, more evidence exists that points towards the oncogenic functions of PKIB in a variety of cancer types." (PMID 38731883, 2024). "Three genetic regulators of PKIB expression have been identified in various cancers." (PMID 38731883, 2024). "Additionally, PKIB impacts cancer cell behavior through two mechanisms; the first is the nuclear modulation of transcriptional activation and the second is the regulation of oncogenic AKT signaling." (PMID 38731883, 2024). "Additionally, the potential impact of microRNA495 on the PKIB/AKT axis would be of great value in cancer research and treatment." (PMID 38731883, 2024). "Additionally, the AP1 transcription complex is heavily involved in T-cell activation, leading to T-cell exhaustion in cancer, thus tying PKIB into the well-known carcinogenic potential of the AP1 mechanisms." (PMID 38731883, 2024). "Moreover, the adjacence of CRE to the leucine zipper component of AP1 further implicates a potential role of PKIB-mediated feedback leading to increasing cancer progression." (PMID 38731883, 2024). "PKIB expression is often correlated with decreased cancer patient prognosis, with one exception." (PMID 38731883, 2024). "Additionally, PKIB contributes to a significant signaling cascade for the field of cancer biology, the well-known PI3K/AKT (AKT is sometimes called PKB or Rac) signaling cascade." (PMID 38731883, 2024). "Through the modification and regulation of these three signaling pathways, estrogen/androgen, E-cadherin/vimentin, and the PI3K/AKT cascade, PKIB has important cytosolic roles in cancer development, metastasis, and proliferation/evasion of apoptosis, respectively." (PMID 38731883, 2024). "Thus, PKIB requires further investigation into both the healthy and cancerous states to fully understand the relevance in carcinogenesis and cancer treatment." (PMID 38731883, 2024). "We next compared PKIB expression in 15 cancer cell lines across the 10 cancer types." (PMID 37434432, 2023). "The exact mechanism through which PKIB governs tumor progression remains unclear, especially the direct substrate of PKA kinase in tumor malignant progression mediated by PKIB and the overexpression regulation of PKIB in cancer cells, all of which demand further exploration." (PMID 40593489, 2025). "However, less is known about the impact of PKIB in cancer development and therapeutic strategies." (PMID 38731883, 2024). "The three PKI isoforms all share some specificity to bind to the PKA-c, but PKIB has the least inhibitory binding effect on PKA-c, thus the focus on PKIα in cancer studies." (PMID 38731883, 2024). "After treating BLCA cells with gemcitabine, the expression of MYCN and PKIB decreased over time, while the expression of p-HSP27 increased gradually, consistent with the inhibitory effects of these protein expression changes on cancer cells." (PMID 40593489, 2025). "Therefore, PKIB was considered a novel possible therapeutic target for BRCA, especially in the cancer classification, diagnosis and precise therapy of BRCA." (PMID 40778650, 2025). "PKIB overexpression is a common feature in multiple malignancies, suggesting that this PKIB-PKA-HSP27 regulatory axis may have broader implications across different cancer types." (PMID 40593489, 2025). "Furthermore, our findings highlight PKIB’s potential as a therapeutic target and its unique function as an endogenous PKA-specific inhibitor, offering valuable translational implications for cancer research and targeted therapy." (PMID 40593489, 2025). "Given that the important roles of PKA in different cancer types may be mediated by different substrate proteins, we conducted a phosphoproteomic analysis using PKIB-knockdown T24 cells to identify potential PKA substrates regulated by PKIB in BLCA." (PMID 40593489, 2025). "To date, the oncogenic molecular mechanism of PKIB in various cancers has not been determined." (PMID 40593489, 2025).
cancer (continued). "PKIB interacts with the immune system in several ways, from the PKIB-expressing classical dendritic cell-induced activation of T-cells to the AP1/PKIB-induced immune system interactions, which could both have far-reaching consequences in cancer." (PMID 38731883, 2024).
tumor (9 papers, 2015 to 2025). "This was further confirmed by immunohistochemical (IHC) staining of tumor tissues from sacrificed mice, which showed lower expression of Ki-67 in PKIB-deficient tumor tissues than in control tissues." (PMID 40593489, 2025). "In this study, we elucidated the critical roles and molecular mechanisms of the PKIB as a tumor promoter in BLCA." (PMID 40593489, 2025). "PKIB-mediated phosphorylation of HSP27 at these three serine residues results in a tumor suppressor effect." (PMID 40593489, 2025). "The tumor tissue volume in mice engrafted with PKIB-knockdown cells was considerably smaller than that in control mice." (PMID 40593489, 2025). "In lung cancer, PKIB was identified as one of the genes correlated with tumor recurrence following surgical resection, although the mechanism for this has not been clarified." (PMID 38731883, 2024). "Together, the interactions between PKIB signaling and genetic regulation can contribute not only to the development of treatment resistance but also to tumor recurrence in cases where the tumors were successfully treated." (PMID 38731883, 2024). "In tumor development, the levels of several transcriptional activators have been correlated to PKIB." (PMID 38731883, 2024). "The data indicated that CDKN2A, TTC39C, and PKIB exerted critical functions in modulating tumor immunity of LUAD." (PMID 35832557, 2022). "A large number of reports indicated that PKIB was a functional partner of Akt and played an important role especially in Akt phosphorylation and signal transduction of tumor cells." (PMID 32676926, 2021). "Furthermore, we used in vivo tumor models to assess the potential of targeting PKIB to suppress BLCA metastasis and proliferation." (PMID 40593489, 2025). "The tumor microenvironment is heavily influenced by immune cells and immune cell penetration, so PKIB interactions in both tumor and immune cells may be synergistic." (PMID 38731883, 2024). "Besides, several other cancer studies have shown that PKIB overexpression promoted the occurrence and development of tumor through the Akt pathway, such as non-small cell lung cancer and breast cancer." (PMID 32676926, 2021). "Indeed, the tumor growth rate was decreased by PKIB knockdown." (PMID 40593489, 2025). "The results presented in this manuscript provide critical molecular and biological insights into the role of the PKIB, an endogenous PKA inhibitor, in tumors, as an oncogene and a driver of tumor cell proliferation and invasion in BLCA." (PMID 40593489, 2025). "Our findings indicate that PKIB facilitates a reduction in the phosphorylation of the novel substrate protein HSP27 by inhibiting PKA kinase activity, thereby promoting tumor cell proliferation and migration." (PMID 40593489, 2025). "VEGFA, PKIB and TMPRSS2 were increased by FGF23 stimulation in LNCaP cells while the tumor suppressor TXNIP was decreased." (PMID 26019137, 2015). "In this instance, PKIB appears to act as a tumor suppressor, although no mechanism for this activity has been shown yet." (PMID 38731883, 2024).
PKIB also shares sentences with these, for which no sentence is quoted: triple-negative breast carcinoma (2 papers); acute myeloid leukemia (1); bladder urothelial carcinoma (1); breast invasive carcinoma (1); glioblastoma multiforme (1); Insulin resistance (1); kidney chromophobe (1); Obesity (1); prostate adenocarcinoma (1); rheumatoid arthritis (1); soft tissue sarcoma (1); stomach adenocarcinoma (1).